SEMA4D (semaphorin 4D)
Diseases named in the same sentence as SEMA4D in open-access papers (continued):
Sharing a sentence is not in itself a finding about the gene and the disease.
tumor (continued). "It is possible that SEMA4D silencing may prevent TAM infiltration and polarization in tumor stroma which is potentially required for SEMA4D production." (PMID 34337054, 2021). "Stable silencing of Plexin-B1 impaired Sema4D-mediated activation of the RhoA and SRPK1 signaling in tumor cells, and resulted in a reduction of microvessel density in xenografts generated in vivo, due to an unknown mechanism." (PMID 31052281, 2019). "Thus, interaction between Sema4D expressed in GBM cells and Plexin-B1-expressing NK cells seems to promote the NK-cell-mediated killing of tumor cells." (PMID 31052281, 2019). "Interestingly, knockdown of Sema4D in a HNSCC cell line, showed inhibition of collagen production by fibroblasts and a decrease in activated TGF-β1 levels in culture medium of tumor cells." (PMID 29541402, 2018). "Constitutive activation of Met in tumor cells with high Plexin-B1 can occur in the absence of Sema4D." (PMID 29971044, 2018). "To investigate whether Sema4D and PDL-1 were differentially expressed within tumor tissue, we assessed for PD-L1 expression in the same HNSCC tumor set studied for Sema4D." (PMID 29541402, 2018). "Sema4D is over expressed in HNSCC, prostate, colon, breast, lung, cervical and ovarian malignancies and it was described to induce tumor angiogenesis through binding to its high affinity receptor Plexin-B1 on endothelial cells promoting their proliferation and organization." (PMID 29541402, 2018). "Sema4D+ve/high expression in tumor cells correlated significantly with dense fibrotic non-inflamed peri-tumoral stroma and inversely with infiltrating Sema4D+ve/high TAIs." (PMID 29541402, 2018). "To further investigate whether Sema4D can directly induce production of TGF-β1 by HNSCC cells and conversely if inhibition of Sema4D would affect the production of TGF-β1 by tumor cells, we used the HN6 stable Sema4D knockdown and controls." (PMID 29541402, 2018). "In preclinical models, anti-SEMA4D reduced the function of MDSC and Treg in the TME while simultaneously restoring the ability of dendritic cells and cytotoxic T cells to migrate into the tumor." (PMID 30400822, 2018). "Moreover, FGF13, SEMA4D, PAPD6B and NRCAM were found to be commonly up-regulated in both cells and tumours." (PMID 30208958, 2018). "However, because excess Sema4D could tip the balance of bone homeostasis in favor of resorption, and we have observed that many carcinomas overexpress Sema4D, we wanted to examine if tumor cells could be using this pathway to establish lytic metastatic lesions in the skeleton." (PMID 26910109, 2016). "Mice injected with tumor cell lines that failed to express Sema4D also exhibited an improved long term survival compared to controls over the course of the experiment." (PMID 26910109, 2016). "It should be noted that Sema4D and PlexinB1 do not always appear to have a tumor-promoting effect, but can also function as tumor-suppressors." (PMID 25815459, 2015). "A study using Sema4D-expressing melanoma transplants in Plexin-B1 knockout mice, however, showed no significant impairment in tumor angiogenesis." (PMID 20858260, 2010). "Moreover, it was reported that Sema4D alone can elicit a significant angiogenic response to promote tumor growth independent of VEGF in colorectal cancer." (PMID 37986114, 2023). "In addition, Semaphorin 4D (Sema4D) and its receptor, Plexin-B1, were found to cooperate with VEGF to promote angiogenesis and tumor progression through attracting Plexin-B1-expressing endothelial cells into the tumor to enhance growth and vascularity." (PMID 37986114, 2023). "HNSCC with Sema4D-positive tumor cells correlated with dense noninflamed peritumoral stroma, and in vitro models showed that HNSCC produced sSema4D can upregulate myeloid-derived suppressor cells (MDSC) and plays a role in extracellular matrix (ECM) deposition by fibroblasts." (PMID 36338570, 2022).
tumor (continued). "Moreover, given the relevance of Sema4D both in cancer and stromal cells, VX15/2503 could act by interfering with the crosstalk between tumor cells and cells belonging to the tumor microenvironment." (PMID 33858502, 2021). "However, in the tumor microenvironment, they frequently change their gene expression profile and behave as M2 macrophages that secrete pro-angiogenic factors such as VEGF, PlGF and sema4D to promote tumor angiogenesis and tumor progression." (PMID 30696103, 2019). "Interestingly, in the limited number of SGA samples examined, Sema4D+ve/high tumor cells with non-inflamed stroma predominated." (PMID 29541402, 2018). "Non-osteoblast and tumor sources of Sema4D could still inhibit osteoblast activity by direct cell:cell contact." (PMID 29971044, 2018). "Also, if Sema4D+ve/high TAIs provide a positive feedback in stage IV malignancy in which the tumor cells are Sema4D-ve/low is not clear at this point." (PMID 29541402, 2018). "We do not postulate a role for Sema4D/Plexin-B1 signaling in the ability of certain tumor cell types to home to bone, but once at the site the end result of such alteration in osteoblast-osteoclast communication would be a more favorable microenvironment in which to establish a metastatic niche." (PMID 26910109, 2016). "Therefore, the involvement of SEMA4D in immunity during tumour development is not known and SEMA4D function in cancer remains ambiguous." (PMID 18781179, 2008). "Additionally, Sema4D mAb did not inhibit MOC1-tumor cell growth or tumor vascularity." (PMID 35155237, 2022). "However, two of the D283 SEMA4D OE animals exhibited extensive subarachnoid space tumor cell spread (data not shown), suggesting that SEMA4D may be contributing to a phenotypic switch in vivo." (PMID 29377567, 2018). "The current findings of Sema4D expression in tumor cells and in TAIs, in addition to our previous in vitro studies showing that HNSCC can produce soluble Sema4D in the tumor CM, raised the question of whether soluble Sema4D can be detected in the peripheral blood of HNSCC patients." (PMID 29541402, 2018). "Inhibition of Sema4D in HN6 cells using shRNA, significantly reduced the level of activated TGF-β1 in the CM of the tumor cells to levels comparable to NOK and to that present in normal cell culture medium." (PMID 29541402, 2018). "PlexinB1 is known to transduce Sema4D signals in vitro and it is expressed in HUVEC endothelial cells and in the tumour vessels in vivo, however its requirement in tumour angiogenesis has not been clearly established." (PMID 17519029, 2007).
cancer (68 papers, 2008 to 2026). A tumor composed of atypical neoplastic, often pleomorphic cells that invade other tissues. "SEMA4D encodes semaphorin 4D which is inhibited by pepinemab, an antibody that has been clinically studied for treatment of several cancer types, including a phase I trial of CRC (Clinicaltrials.gov: NCT03373188)." (PMID 40447568, 2025). "On the other hand, it was also reported that Sema4D expressed on the cellular membrane of cancer cells is shed by Membrane Type‐1 Matrix Metalloproteinase (MT1‐MMP) which has been implicated in cancer metastasis." (PMID 37170687, 2023). "Although we addressed the possible role of Sema4D in bone remodeling processes, the multifunctional molecule Sema4D is implicated in cancer angiogenesis, as well as axonal guidance during neuronal development." (PMID 35628440, 2022). "Sema4D and Plexin-B1 are abnormally expressed in various cancers and have been associated with invasive phenotypes and poor prognosis." (PMID 29971044, 2018). "Plexin-B family members contribute to cancer progression, for example Sema4D induces invasive growth of cancer cells by signalling through Plexin-B1, which associates with and activates the tyrosine kinase receptors Met or Ron." (PMID 29040270, 2017). "With respect to c-Met, plexin B1 and its ligand, semaphorin 4D, have been most studied, and both have been implicated in cancer progression." (PMID 28536399, 2015). "SEMA4D expression has been associated with bone metastasis in breast and distant metastasis across various other cancers, which led to the development of the monoclonal antibody pipinemab, currently undergoing clinical evaluation in breast, pancreatic and head and neck cancers." (PMID 37685898, 2023). "Moreover, depletion of TAMs by Sema4D blockage to decrease M2-Mφs recruitment and aggregation, to eliminate TAMs-associated angiogenesis and metastasis, is a potential strategy to cancer treatment." (PMID 35155237, 2022). "As for other cancers, Sema4D expression has furthermore been associated with CRC development." (PMID 33537086, 2021). "Our framework also prioritises SEMA4D, a previously unreported CRC susceptibility gene encoding a protein targeted by investigational cancer therapies." (PMID 40447568, 2025). "Further analysis of ligand-receptor pairs revealed that VTN-(ITGAV + ITGB5), SEMA4D-PLXNB2, GAS6-TYRO3, and FN1-(ITGA3 + ITGB1) were more prevalent in high-risk cancer cells." (PMID 41034991, 2025). "Immune-modulating proteins such as CXCR4, CD40, IL7R, TGFBR1, and SEMA4D are frequently targeted for cancer intervention studies." (PMID 40805206, 2025). "Genes LGALS8, PDE4DIP, RAD17, ELN, MUC4 and SEMA4D had a mid-range expression in both cancer types, while OPRM1 and ADRA1 were the least expressed, thereby corroborating the results from our box plot and survival analysis." (PMID 38544823, 2024). "Semaphorins (such as SEMA3D and SEMA4D) are characterized by aberrant expression in several cancer types and contribute to cancer initiation." (PMID 39766161, 2024). "They found significantly higher expression of sema4D mRNA in cancer tissue compared to healthy bladder tissue." (PMID 39061999, 2024). "SEMA4D expression has been frequently observed in various human cancers as well as craniofacial tissues." (PMID 37504226, 2023). "This is not surprising, since divergent semaphorin functions in neurons and in cancer cells are commonly seen (e.g. for Sema3A, Sema3E, Sema4D, etc.), likely reflecting the involvement of different receptor complexes and signaling pathways." (PMID 37002363, 2023). "It is also reported that the soluble form of Sema4D (sSema4D) is secreted by γδ T and cancer cells, as well as platelets and osteoclasts." (PMID 37170687, 2023). "Preclinical studies have shown that therapeutic intervention using SEMA3A/SEMA4D antibodies to decrease TAMs is a potential strategy for cancer treatment." (PMID 37685898, 2023).
cancer (continued). "Most importantly, some studies have revealed that the functions of Plexins in cancers are regulated by semaphorins, including Sema3C, Sema4D, and Sema5A." (PMID 37901456, 2023). "The cancer tissues and para carcinoma tissues from each patient were collected for IHC staining and RT–qPCR to explore the expression of the SEMA4D protein and mRNA." (PMID 37287907, 2023). "Human semaphorin 4D (Sema 4D) is highly expressed in a variety of aggressive cancers and serves as a compensatory angiogenic factor to potentiate cancer growth and angiogenesis." (PMID 35884547, 2022). "In particular, the treatment with an anti-Sema4D antibody was found to promote anti-cancer immune response in mouse models by favoring the recruitment of cytotoxic T lymphocytes 44,45." (PMID 33537086, 2021). "Sema4D, derived from cancer cells, induces the formation of peripheral blood mononuclear cells into MDSCs in vitro." (PMID 34403220, 2021). "After the demonstration of safety of VX15/2503, an anti-Sema4D antibody, in patients with advanced solid tumors, several clinical studies are recruiting cancer patients to analyse the efficacy of this antibody in combination with immune checkpoint inhibitors." (PMID 33858502, 2021). "Humanized anti-Sema4D antibody is currently under investigation in cancer and autoimmune neurogenic disorders." (PMID 33776991, 2021). "Since SEMA4D promotes invasion and metastasis of cancers, this study indicates that LINC01061 functions as ceRNA for SEMA4D by sponging miR-612 leading to cell proliferation and migration of CCA cell lines." (PMID 32154257, 2020). "Sema4D, as a member of the semaphorin family, is a multifunctional protein that plays important roles in the immune response, cancer progression, neuroinflammation, and neurodegeneration." (PMID 31943789, 2020). "Semaphorin 4D (Sema4D), which is implied in the growth of neuronal system, can restrain integrin-mediated cancer cell invasion and migration through inducing Ras-specific GAP Plexin-B1 via direct protein–protein interaction." (PMID 30884855, 2019). "While blocking the Sema4D/Plexin-B1 complex is of potential benefit in cancers and neuroinflammatory diseases, some cancers are growth inhibited by Sema4D signaling." (PMID 29971044, 2018). "Most studies concerning the role of Sema4D in cancer indicate a pro-tumoral activity of this semaphorin acting on the diverse components of cancer development and progression, including cancer cells, blood vessels, infiltrating macrophages, etc.." (PMID 30134791, 2018). "The role of Sema4D in immune regulation supports the importance of dysregulated Sema4D in immune escape of cancer cells." (PMID 29971044, 2018). "This review focuses on additional, emerging roles of Sema4D in bone biology and cancer bone metastases." (PMID 29971044, 2018). "Because of its known role in lymphoid cells, Sema4D expression in cancer was first evaluated in lymphoma and lymphoblastic leukemia." (PMID 29971044, 2018). "The involvement of Sema4D in bone biology and cancer progression suggests a role in bone metastasis." (PMID 29971044, 2018). "As a result, the downregulation of Sema4D and its receptor expression can be an attractive immunotherapeutic approach for the treatment of many types of cancer." (PMID 30134791, 2018). "We have previously shown that many cancers, particularly those of epithelial origin, overexpress Sema4D and therefore wanted to examine the biological significance in bone metastasis." (PMID 26910109, 2016). "We have previously shown that Sema4D is secreted or shed into the media in cancer cells expressing it through the action of a protease." (PMID 26910109, 2016). "ErbB-2 phosphorylation and RhoA activation are required for several downstream cellular effects including the promigratory and prometastatic effects of semaphorins on cancer cells and Sema4D-induced axonal growth cone collapse." (PMID 25137062, 2014).
cancer (continued). "Metalloproteinase ADAM17 and MT1-MMP have been identified to shed Sema4D from the surface of platelets and cancer cells." (PMID 23741311, 2013). "Interestingly, disrupting the interaction of Sema4D with Plexin-B1 receptor has been shown to hinder the transmigration of cancer cells in an in vitro experimental model of the BBB." (PMID 37190188, 2023). "Sema4D promotes the proliferation and metastasis of cancer cells." (PMID 35401878, 2022). "Due to its important role in inflammation, Sema4D is also involved in cancer progression." (PMID 35401878, 2022). "Previous studies reported that semaphorins members play important regulatory roles in the development of the nervous system (Sema3A, 3F, 4D, 6C, 6D, 7A), immune system (Sema4D), reproductive systems (Sema3), cancer progression (Sema3A, 4D, 6D) and the vascular system (Sema3A, 3E, 4D, 6D)." (PMID 36010604, 2022). "As a result, the therapeutic medication VX15/2503, which targets SEMA4D, may provide a novel cancer treatment method." (PMID 35794581, 2022). "Thereby, this might conclude a possible alternative to cancer therapy by targeting several prominent pathways involved in cancer through SEMA4D suppression." (PMID 34337054, 2021). "We found that knockdown of VEGF could suppress SEMA4D expression and that the expressions of VEGF and SEMA4D have a positive correlation in EOC cancer tissues." (PMID 29308068, 2018). "Targeting Sema4D in the clinic has become practical with the development of a specific neutralizing antibody, which has low toxicity and an impressive response rate in early clinical trials of patients with refractory cancers." (PMID 29971044, 2018). "While not directly linked to malignant transformation, Sema4D/Plexin-B1 signaling contributes to many critical aspects of cancer progression, including proliferation, invasion, angiogenesis, immune escape, and metastasis." (PMID 29971044, 2018). "In cancer cells that express both Sema4D and Plexin-B1, the pair could function in an autocrine/paracrine manner, although this requires future study." (PMID 29971044, 2018). "Although, the expression of Sema4D and PlexinB1 have been investigated in some solid malignancies, the correlation between the expression of these factors and the prognosis of patients with malignant tumors remains controversial." (PMID 27456345, 2016). "Since Sema4D is expressed in T-cells and certain types of cancer cells, Plexin-B1-mediated and IKK-complex-dependent RhoA activation might contribute to reduced bone formation under these circumstances." (PMID 25137062, 2014). "The reciprocal effect of c-Met and ErbB2 in plexin-B1-mediated regulation of RhoA activation status is believed to partially account for the pro- and antimigratory effects of Sema4D in breast carcinoma and other cancer cells, depending on the relative expression levels of these two receptors." (PMID 23050142, 2012). "Therefore, the PLXNB1/SEMA4D axis may be a relevant cancer biomarker that warrants further investigation, with SEMA4D's specific role in CRC remaining unclear." (PMID 39443302, 2024). "Moreover, sema4D was able to promote cancer cells’ viability and metastases." (PMID 39061999, 2024). "DHM has been demonstrated to significantly lower Sema4D expression in vivo and in vitro, resulting in a reduction in inflammatory invasion and limiting the expression of inflammatory factors and MDA levels in CoLo-205 colorectal cancer cells, reducing the risk of cancer development." (PMID 35884547, 2022). "Notably, recent data challenged the view that targeting Sema4D in tumors is always beneficial 47, suggesting that further investigation may be help to exploit Sema4D at its best as therapeutic target in cancer." (PMID 33537086, 2021). "Thus, based on these data, targeting Sema4D could represent a treatment option for cancer patients developing adaptive resistance to anti-VEGF drugs." (PMID 33537086, 2021).